RUVBL1 (RuvB like AAA ATPase 1)
Diseases named in the same sentence as RUVBL1 in open-access papers (continued):
Sharing a sentence is not in itself a finding about the gene and the disease.
pancreatic cancers (5 papers, 2019 to 2025). "Since the complete loss of RUVBL1 is embryonically lethal, we analysed if CB-6644 affects pancreatic cancer progression in vivo at tolerated doses." (PMID 38821858, 2024). "Finally, by revealing the nuclear functions of the RUVBL1/2 complex, our study presents a pharmaceutical strategy to render pancreatic cancers potentially susceptible to immunotherapy." (PMID 38821858, 2024). "RUVBL1 depletion mimicked cellular phenotypes previously observed on MYC depletion in pancreatic cancer cells." (PMID 38821858, 2024). "Overall, we concluded that high MYC expression renders pancreatic cancer cells dependent on RUVBL1/2 and that inhibition of the RUVBL1/2 complex is therapeutic at doses tolerated by healthy tissues." (PMID 38821858, 2024). "We concluded that RUVBL1 is required for the maintenance and progression of pancreatic cancer in mice." (PMID 38821858, 2024). "We concluded that depletion of RUVBL1 in pancreatic cancer leads to immune infiltration and induces tumour sensitivity to immune checkpoint blockade." (PMID 38821858, 2024). "We assumed that daily administration of auxin would result in durable RUVBL1 depletion, enabling us to investigate the role of RUVBL1 in pancreatic tumour progression." (PMID 38821858, 2024). "We observed that oncogenic MYC expression renders cells dependent on the activity of the RUVBL1/2 complex and that acute depletion or inhibition of RUVBL1 provokes immune infiltration and eradicates pancreatic tumours in mice." (PMID 38821858, 2024). "We concluded that RUVBL1 depletion in pancreatic tumours induces immune cell infiltration and therefore phenocopies the genetic silencing of MYC in similar tumour models." (PMID 38821858, 2024). "Since MYC promotes immune evasion in pancreatic tumours, 35 51 we analysed immune cell infiltration on RUVBL1 depletion and observed a rampant increase in CD3-positive cells within tumours on auxin treatment." (PMID 38821858, 2024). "Based on the GENT database, we showed that both LASP1 and RUVBL1 gene expression were significantly upregulated in pancreatic cancer tissues and were positively correlated with ANLN expression." (PMID 31395079, 2019). "To this end, we first quantified MYC and RUVBL1 levels in a panel of pancreatic cancer cells by immunoblotting and observed a strong correlation between the levels of both proteins and between their levels and sensitivity to CB-6644 as estimated in cell growth assays." (PMID 38821858, 2024). "Based on the GENT database, we showed that both LASP1 and RUVBL1 gene expression were significantly upregulated in pancreatic cancer tissues compared with that in normal pancreatic tissues, while RAB11B was not changed obviously, and MYO1B was significantly downregulated." (PMID 31395079, 2019). "To test whether activation of MYC target genes and repression of immune genes is a general function of RUVBL1 in pancreatic cancer cells, we treated five further murine PDAC lines with different genetic backgrounds with CB-6644 for 24 hours and analysed gene expression by RNA sequencing." (PMID 38821858, 2024). "We concluded that RUVBL1 and MYC co-occupy thousands of promoters in pancreatic cancer cells and that depletion or inhibition of RUVBL1 leads to their downregulation." (PMID 38821858, 2024). "A comparison with KPC cells revealed that only RUVBL1, RUVBL2, TRRAP, SPT6 and WDR5 were essential in pancreatic tumours and more important for KPC cells than fibroblasts (Δlog2FC<0)." (PMID 38821858, 2024). "We concluded that MYC and the RUVBL1/2 complex bind to each other, explaining their co-occupancy on thousands of promoters and the relevance of RUVBL1 for MYC-mediated gene regulation and growth of pancreatic cancer cells." (PMID 38821858, 2024). "(A) Based on the GENT database, LASP1, RAB11B, RUVBL1 and MYO1B gene expression were analyzed in the pancreatic cancer tissues and normal pancreatic tissues." (PMID 31395079, 2019).
pancreatic cancers (continued). "We wondered whether the dependence of pancreatic tumours on the RUVBL1/2 complex is conveyed by high MYC expression, so we did a series of experiments using the RUVBL1/2 inhibitor CB-6644 to address this question." (PMID 38821858, 2024). "(C) CCK-8 assay showed that LASP1 restoration partially reversed the effects of ANLN knockdown on pancreatic cancer cell proliferation, while RUVBL1 restoration did not reverse the effect of ANLN downregulation on pancreatic cancer cell proliferation." (PMID 31395079, 2019). "However, RUVBL1 restoration did not reverse the effect of ANLN downregulation on pancreatic cancer cell proliferation." (PMID 31395079, 2019).
colon cancer (4 papers, 2013 to 2025). "Immunofluorescence (IF) demonstrated the colocalization of Lyn and RUVBL1 in colon cancer cell lines, CRC tissues, and CRC liver metastases." (PMID 39665272, 2025). "Survival analysis of stage 3 colon cancer patients via a Kaplan–Meier plotter revealed poor outcomes in patients with high expression of Lyn and RUVBL1." (PMID 39665272, 2025). "The control group of liver‐inoculated nude mice presented a high number of visible tumor nodules in the liver, whereas the nude mice with stable silencing of Lyn and RUVBL1 colon cancer cells presented a lower number of tumor nodules in the liver." (PMID 39665272, 2025). "Nude mice inoculated with stably silenced Lyn and RUVBL1 colon cancer cell lines developed tumor nodules in the spleen, along with a few visible tumor nodules in the liver." (PMID 39665272, 2025). "Bioluminescence imaging revealed a significant reduction in the fluorescence signal in nude mice following liver inoculation with colon cancer cells in which Lyn and RUVBL1 were silenced." (PMID 39665272, 2025). "We found that inhibiting Lyn and RUVBL1 significantly reduced colon cancer cell migration and invasion." (PMID 39665272, 2025). "To further investigate the effects of Lyn/RUVBL1 on the epigenetics of colon cancer cells, we examined whole‐genome H3K27ac levels using CUT‐Tag." (PMID 39665272, 2025). "Visual analysis revealed a decrease in the chromatin accessibility of β‐catenin in colon cancer cells following the suppression of Lyn/RUVBL1." (PMID 39665272, 2025). "In summary, the Lyn/RUVBL1 complex regulates AA metabolism in colon cancer cells by upregulating COX2 through FOXA1." (PMID 39665272, 2025). "Survival analysis revealed that compared with control nude mice, nude mice inoculated with silenced Lyn and RUVBL1 colon cancer cells had significantly longer lifespans." (PMID 39665272, 2025). "Stable colon cancer cell lines were generated and injected into nude mice to study the effect of the Lyn/RUVBL1 complex on CRC metastasis." (PMID 39665272, 2025). "Conversely, suppressing RUVBL1 in colon cancer cells also decreased Lyn levels." (PMID 39665272, 2025). "RUVBL1 is reported to regulate COX-2 gene expression that plays a crucial role in the progress and transformation of colon cancer." (PMID 24396308, 2013). "Importantly, most of WNT pathway genes induced by MYC, including DVL1, LEF1, RUVBL1, and RUVBL2, were also upregulated in tumor tissues when compared with the normal tissues from the same patients, suggesting that these genes may play a major role in colon cancer cells." (PMID 31623618, 2019).
lung adenocarcinoma (4 papers, 2021 to 2024). A carcinoma that arises from the lung and is characterized by the presence of malignant glandular epithelial cells. "In addition, silence of RUVBL1 exerts inhibitory effect on malignant cell proliferation both in vitro and in vivo in the context of prostate tumor as well as lung adenocarcinoma." (PMID 37076452, 2023). "Likewise, a mechanistic report has pointed to the anti-proliferative activity of downregulated RUVBL1 in lung adenocarcinoma by arresting G1/S phase cell cycle, supporting the validation of our experimental data." (PMID 37076452, 2023). "This analyses identified four proteins—Pdhx, Psma6, Ruvbl1, and Ywhaq—that were increased in abundance as a result of ECS exposure and also amplified in human lung adenocarcinomas." (PMID 39273313, 2024). "Through the regression analysis, the increased RuvBL1 was linearly related to the decreased c-Jun in lung adenocarcinoma, indicating a negative correlation expression of RuvBL1 and c-Jun." (PMID 34164343, 2021). "Moreover, there was a negative correlation expression between RuvBL1 and c-Jun in lung adenocarcinoma by Oncomine analyses." (PMID 34164343, 2021).
liver cancer (3 papers, 2022 to 2025). An epithelial or non-epithelial malignant neoplasm that arises from the liver. "Such interaction occurs not only in cells, but also are present in established tumors of mice, underlying the physical importance of RUVBL1-HPCAL1 interaction in liver cancers." (PMID 36438486, 2022).
myositis (3 papers, 2016 to 2023). "Similarly to autoantibodies against PM/Scl and Ku, anti-RuvBL1/2 are associated with SSc/myositis overlap, but anti-RuvBL1/2 positive overlap patients were found to have more frequently gastrointestinal and heart involvement than those with anti PM/Scl or anti Ku." (PMID 35716254, 2023). "Patients in which the Ruvbl1/2 autoantibodies were detected showed more myositis and diffuse skin thickening and a high frequency of diffuse cutaneous involvement." (PMID 33580312, 2021).
neuroblastoma (3 papers, 2012 to 2026). Neuroblastoma (NB) is the most common solid, extracranial childhood tumor. "CSNK2A1 and RUVBL1 have been reported to play multiple roles in driving malignant transformation, and RUVBL1 expression was identified to be associated with poor overall survival in neuroblastoma patients." (PMID 23226679, 2012).
oral squamous cell carcinoma (3 papers, 2022 to 2024). "Also, the prognostic and diagnostic potential of RUVBL1 in oral squamous cell carcinoma has been uncovered." (PMID 37076452, 2023).
viral infection (3 papers, 2014 to 2024). "RUVBL1/2 have individually as well as dually been implicated in viral infections." (PMID 31018511, 2019). "Furthermore, silencing of RUVBL1 led to increased viral infection in human cultured cells and primary mouse neurons." (PMID 24550726, 2014).
Fanconi anaemia (2 papers, 2014 to 2015). "Knock-down of RUVBL1/2 shows similar phenotype as depletion of the Fanconi anemia core complex proteins and conditionally knock-out cells depleted from RUVBL1/2 have highly reduced levels of the Fanconi anemia core complex proteins." (PMID 25767478, 2015).
Multiple Myeloma (2 papers, 2024). "As an inhibitor specific to the RUVBL1/2 complex, CB-6644 exhibits remarkable anti-tumor activity in xenograft models of Burkitt’s lymphoma and multiple myeloma (MM)." (PMID 39201707, 2024).
oral cancer (2 papers, 2022 to 2025). "Hub genes VRK1, NUP37, HMMR, SPC25, and RUVBL1 were identified to be related to oral cancer at both molecular level and clinical levels." (PMID 36052378, 2022).
prostate carcinoma (2 papers, 2013 to 2024). A carcinoma that arises from epithelial cells of the prostate gland. "A genome-wide association study also suggests that elevated RUVBL1 increases cell proliferation and tumour growth, further suggesting an association between RUVBL1 expression and prostate cancer progression." (PMID 39402324, 2024). "In prostate cancer, RUVBL1 has been associated with Enzalutamide resistance." (PMID 39402324, 2024). "With the 5-gene prostate cancer metastasis signature panel comprised of U2AF2, RUVBL1, STMN1, HDGF, and FABP4, we further assessed the power of prediction of this gene signature panel in two different, independent public patient datasets (Grasso CS, Nature, 2012; Varambally S CS, Cancer Cell, 2005)." (PMID 39402324, 2024). "We show that URI interacts with RUVBL1 and RUVBL2 in the nucleus of prostate cancer cells." (PMID 23667685, 2013).
psoriasis (2 papers, 2015 to 2023). An autoimmune condition characterized by red, well-delineated plaques with silvery scales that are usually on the extensor surfaces and scalp. "The expression levels of phospholipid scramblase 1 (PLSCR1), heme binding protein 1 (HEBP1), structural maintenance of chromosomes 4 (SMC4), and RuvB like AAA ATPase 1 (RUVBL1) genes were shown to be reversed by candidate compounds for psoriasis using the RORUCI values." (PMID 37035327, 2023). "Several TFs/uDBPs additionally showed altered expression in blood from psoriasis patients (increased: JUNB, STAT3, DTL, CAT; decreased: CUX2, ZNF559, AVEN, RUVBL1, RAN)." (PMID 25883770, 2015).
renal cell carcinoma (2 papers, 2019 to 2022). "This corresponds with in vitro experiments demonstrating that RUVBL1 was predominantly expressed in the cytoplasm of renal cell carcinoma cell lines and pancreatic ductal adenocarcinoma cell lines." (PMID 36242708, 2022). "Depletion of RUVBL1 in renal cell carcinoma significantly decreased nuclear β-catenin expression and it was hypothesized that RUVBL1 may promote the relocation of β-catenin from the cadherins junctions to the nucleus." (PMID 31665067, 2019).
systemic sclerosis (2 papers, 2021 to 2023). A chronic disorder, possibly autoimmune, marked by excessive production of collagen which results in hardening and thickening of body tissues. "A link between Ruvbl1 and skin biology and disease has previously been established by the observation of Ruvbl1 and Ruvbl2 autoantibodies in a subcohort of patients suffering from systemic sclerosis but not from other connective tissue diseases." (PMID 33580312, 2021).
aplastic anaemia (1 paper, 2014). "Genetic knockout of RuvBL1 in a murine model is embryonic lethal while conditional inactivation in the haematopoietic stem cell pool confers profound aplastic anaemia." (PMID 25428364, 2014).
arbovirus infection (1 paper, 2019). A viral infection that is transmitted by an arthropod. "A genome-wide RNAi screen identified RUVBL1 as a host factor that inhibits arbovirus infection in adult flies, mosquito cells, and mammalian cells." (PMID 31018511, 2019).
asthenozoospermia (1 paper, 2023). "In detail, the combination of the three proteins APCS, APOE, and FLOT1 predicts male subfertility in general, the two combined proteins APOE and FN1 predicts asthenozoospermia, and the two combined proteins RUVBL1 and TFKC oligoasthenozoospermia." (PMID 37048090, 2023).
autoimmune hepatitis (1 paper, 2023). Hepatitis caused by autoantibodies. "Anti-RuvBL1/2 antibodies are detected in a small number of patients with various connective tissue diseases (or autoimmune hepatitis (AIH) by ELISA using a recombinant RuvBL fragment expressed in E. coli." (PMID 35716254, 2023).
breast-tumor (1 paper, 2024). "Our research revealed that RUVBL1, also known as pontin/TIP49, is excessively expressed in MMTV-PyMT mouse models undergoing radiotherapy, which is considered a murine spontaneous breast-tumor model." (PMID 38609375, 2024).
cervical cancer (1 paper, 2025). A primary or metastatic malignant neoplasm involving the cervix. "Among these transcripts, AC125616.1, HRG, MAPT, RUVBL1.AS1, and SYTL5 were found to be upregulated, while AC011239.1 and ART3 were downregulated in cervical cancer patients with LNM compared to those without it." (PMID 40444278, 2025).
Clear-Cell Renal Cell Carcinoma (1 paper, 2024). "This study delves into the roles of RUVBL1 and HIF1A in the development of clear-cell renal cell carcinoma (ccRCC) and investigates their clinical relevance as prognostic biomarkers." (PMID 38610951, 2024).
co-infection (1 paper, 2025). "Protein-protein interaction network analysis further delineated pathogen-specific hubs: inflammatory mediators (CXCL8, CCL20, IL6) in the E group, molecular chaperones (CCT5, RUVBL1/2) in the S group, and a distinctive IL6-FBL-centered network in co-infection." (PMID 40771952, 2025).
Ewing sarcoma (1 paper, 2024). A small round cell tumor that lacks morphologic, immunohistochemical, and electron microscopic evidence of neuroectodermal differentiation. "Based on a recent report in Ewing sarcoma, we designed a series of putative loss-of-interaction mutants for RUVBL1 (RUVBL1Δ94-118, RUVBL1Δ102-107, RUVBL1K108A) and tested their interaction in co-immunoprecipitation experiments in KPC cells." (PMID 38821858, 2024).
head and neck squamous cell carcinoma (1 paper, 2023). A squamous cell carcinoma that arises from any of the following anatomic sites: lip and oral cavity, nasal cavity, paranasal sinuses, pharynx, larynx, and salivary glands. "Furthermore, the implication of RUVBL1 in differentiation, proliferation and invasion of head and neck squamous cell carcinoma cells has been documented by incorporating histone variant H2AZ in chromatin, highly suggestive of its functional role in evaluating prognosis." (PMID 37076452, 2023).
leukemia (1 paper, 2015). A malignant (clonal) hematologic disorder, involving hematopoietic stem cells and characterized by the presence of primitive or atypical myeloid or lymphoid cells in the bone marrow and the blood. "RUVBL1 is located on a chromosomal region that is frequently rearranged in leukemia and solid tumors, which further suggests a role for RUVBL1 in leukemogenesis." (PMID 25789315, 2015).
lymph node metastasis (1 paper, 2024). "High RUVBL1 mRNA expression was correlated with a higher histological grade, advanced T stage, lymph node metastasis, and advanced clinical stage." (PMID 38610951, 2024). "Elevated mRNA levels of RUVBL1 were also more frequently detected in patients with lymph node metastases compared to those without cancer cells in the lymph nodes (p = 0.001)." (PMID 38610951, 2024).
male infertility (1 paper, 2019). The inability of the male to effect fertilization of an ovum after a specified period of unprotected intercourse. "In mice, loss-of-function mutations of RuvBL1 is lethal at an early embryonic stage, but deletion of the RuvBL1 only in premeiotic male germ cells causes male infertility." (PMID 31817850, 2019).
scleromyositis (1 paper, 2022). "In contrast, several other autoantibodies (not included in the SSc 2013 ACR/EULAR criteria), such as anti-PM/Scl, -Ku, -U1-RNP, -U3-RNP, - RuvBL1/2, -SMN, have been specifically associated with scleromyositis." (PMID 36776390, 2022).
serous ovarian cancer (1 paper, 2013). "Two SNPs in RUVBL1 were found to be associated with increased risk of serous ovarian cancer." (PMID 24396308, 2013).
uveal melanoma (1 paper, 2023). A melanoma derived from melanocytes of the uveal tract. "Our study was performed to explore the possible carcinogenic mechanism of the chromatin regulator RuvB-like protein 1 (RUVBL1) in uveal melanoma (UVM)." (PMID 37076452, 2023).